IL6 (interleukin 6)
Diseases named in the same sentence as IL6 in open-access papers (continued):
Sharing a sentence is not in itself a finding about the gene and the disease.
heart failure (continued). "Previous studies have shown that omega-3 PUFAs have many beneficial effects in human heart failure including inhibition of proinflammatory response in patients with increased concentration of TNF-alfa, IL-1 and IL-6." (PMID 34944135, 2021). "Pro-brain natriuretic peptide (NPPB), Interleukin-6 (IL6), and their mRNA were the major biomarkers of heart failure." (PMID 32075047, 2020). "Heart failure evokes inflammation, and TNF-α, IL-6, IL-18, and atrial natriuretic peptide (ANP) can be induced in pressure overload-induced heart failure." (PMID 33597865, 2020). "The role of inflammation in heart failure has been proposed as levels of inflammatory cytokines including tumor necrosis factor (TNF), interleukin (IL)-1β and IL-6 were found to be elevated in heart failure." (PMID 33344515, 2020). "In the same manner, amiodarone, an antiarrhythmic drug that improves the long-term prognosis of heart failure, has been shown to inhibit the production of TNF-α and IL-6." (PMID 30935055, 2019). "In particular, pimobendan has been shown to decrease the production of intracardiac IL-1β, IL-6, TNF-α and nitric oxide by inhibiting the activation of NFκB in mouse models of heart failure." (PMID 30935055, 2019). "Statins had also been reported to decrease levels of C-reactive protein, interleukin-6, TNF-α, improve left ventricular function among individuals with heart failure." (PMID 31627722, 2019). "For example, during MI, myocarditis, or heart failure, both tumor necrosis factor α (TNF-α) and interleukin 6 (IL-6) levels increase in proportion to the severity and duration of congestive heart failure (CHF)." (PMID 30104479, 2018). "For example, IL-6, TNF-RI and TNF-RII were significantly higher in the highest RDW patients with heart failure." (PMID 29342203, 2018). "There is considerable evidence that inflammatory cytokines such as IL-6, IL-1 and TNF-α are upregulated in plasma of heart failure patients, as well as in the failing myocardium itself." (PMID 29674727, 2018). "Serum interleukin-6 (IL-6), a proinflammatory cytokine, was positively correlated with RDW in adult patients with heart failure and congenital heart disease." (PMID 29237417, 2017). "One multicenter clinical trial of 1,200 patients with progressed heart failure shows that the up-regulated circulating levels of TNF, IL-6 and the soluble TNF receptors sTNFR1 and sTNFR2 are related with increased mortality." (PMID 28978156, 2017). "Levels of IL-6 are found considerably higher in myocardium and serum of patients receiving LVAD and with advanced heart failure." (PMID 27884156, 2016). "Similar to IL-6, a general inflammatory biomarker C-reactive protein (hsCRP) also correlated with poor DCM prognosis, heart failure and mitochondrion-mediated myocyte apoptosis." (PMID 25888309, 2015). "However, the prolonged activation of NF-κB appears to be detrimental and promotes heart failure by eliciting signals that trigger chronic inflammation through the enhanced elaboration of cytokines, including tumor necrosis factor, interleukin-1, and interleukin-6, leading to cell death." (PMID 26467087, 2015). "A study of heart failure patients found a positive relationship between elevated RDW and serum levels of interleukin 6, an inflammatory cytokine." (PMID 25961836, 2015). "Increased inflammatory cytokines such as IL-6, IL-8 and MCP-1 have been shown to be significant indicators of a greater degree of heart failure with preserved EF." (PMID 23446214, 2013). "The publication bias test was performed using the Begg test which shows that the P value of each outcome indicator was greater than 0.05 (heart failure markers: P = 0.061, CRP: P = 0.602, TNF-α: P = 0.317, and IL-6: P = 0.317), and therefore the possibility of publication bias was low." (PMID 41179565, 2025).
heart failure (continued). "As a retrospective study, one of the primary limitations is the lack of routine evaluation of biomarkers such as lactate dehydrogenase (LDH), ferritin, and IL-6 in patients without chronic cardiovascular conditions, e.g., coronary syndrome or heart failure." (PMID 40143236, 2025). "As previous studies have noted, the induction of specific cytokines, such as IL-6 and TNF-α, plays a detrimental role in the development of adverse ventricular remodeling and subsequent heart failure, contributing to conditions such as cardiac hypertrophy and impaired myocardial contractility." (PMID 39805484, 2025). "Treatment of myocarditis in AOSD has two arms, i.e., non-specific management of heart failure, and disease-specific treatment with corticosteroids, IL-1/IL-6 antagonists, or TNF inhibitors." (PMID 38883113, 2024). "Additionally, cytokines are implicated in the pathogenesis of SFTS, with elevated levels of IL-6, IL-10, TNF-α, and interferon-γ reported in severe cases, including those involving heart failure, compared to healthy adults." (PMID 38389047, 2024). "This overexpression of IL-6 may contribute to cardiovascular diseases, such as CAD, heart failure, and arrhythmias." (PMID 38540106, 2024). "Overall, the data indicate that treatment with SCoV2-epitope leads to an increase in the secretion of proinflammatory cytokine GM-CSF while decreasing the secretion of TNF-α, IL-6, and CCL2, which can contribute to the damage of primary cardiomyocytes and potentially lead to cardiac failure." (PMID 38068877, 2023). "Furthermore, it was found that people with CF had increased levels of interleukin-6 (IL-6) and tumor necrosis factor alpha (TNF-a), which were involved in the development of atherosclerotic plaque and heart failure." (PMID 36678185, 2023). "IL-6 was persistently elevated at 6 and 12 months in non-recovery patients, while IL-17A was associated with fibrosis in DCM patients with class III-IV heart failure." (PMID 37175422, 2023). "Although IL-6 concentration is associated with mortality risk in PAH patients, it is not necessarily an indicator of heart failure." (PMID 37761997, 2023). "Additionally, a similar traditional Chinese medicine, Xinyin Tablet has shown to alleviate heart failure by reducing serum levels of TNF-α and IL-6 and improving cardiac ultrastructure." (PMID 37919806, 2023). "After classification of the AF patients into PAF and PeAF patients, we observed a high heart failure (HF) rate, increased levels of LAD, elevated serum concentrations of BNP, MDA, TNF-α, IL-6, CTX-I, TGF-β1, and lower expression of SOD (P<0.05) in PeAF patients than in PAF patients." (PMID 37275755, 2023). "Proinflammatory cytokines such as TNF-α and IL-6, acting directly on the myocardium at a later stage of DOX-induced cardiac injury, generate additional oxidative/nitrosative stress with hypertrophy and fibrosis, ultimately leading to heart failure." (PMID 37242448, 2023). "Further evidence about the interplay between the heart and the kidney stems from biomarker studies demonstrating that biomarkers of kidney disease progression, such as the ones identified in our study, TNFR-1, KIM-1, IL-6, MMP-7, also predict the composite heart failure outcome." (PMID 36151557, 2022). "While adenoviral overexpression of TCS22 failed to significantly regulate many heart failure-relevant transcripts (including brain natriuretic peptide, Anp, Il6 and Col1a), it did elicit a robust increase in Col3a1 in the LV." (PMID 36388115, 2022). "Beside the classic marker that is CRP (which is an independent prognostic factor for adverse events in patients with heart failure) or NT-proBNP, an increased concentration of TNF- α, ST2, IL-1, IL-6, IL-8, Galectin-3 (Gal-3), and growth differentiation factor 15 (GDF15) was also observed." (PMID 35269577, 2022).
heart failure (continued). "Recent studies have shown that the expression of TNF-α and IL-6 genes increases in CHF patients, and are positively correlated with the severity of heart failure, thus indicating that the expression of pro-inflammatory cytokines is a significant factor in the severity of CHF." (PMID 35734399, 2022). "The addition of heart failure was associated with an additional increase in the level of C-reactive protein, TNF-α, and IL-6 in the blood, regardless of patients’ sex." (PMID 35997392, 2022). "In DOX-induced heart failure mice, SOD2, GPx-1, FOX3a, and SIRT3 expression are decreased, apoptotic cells and cleaved-caspase-3 expression are increased, as well as inflammatory cytokines such as IL-1β, IL-6, and TNF-α are increased." (PMID 34513812, 2021). "Studies have shown that in the absence of C5aR1, the levels of IL-1 beta and IL-6 decreased in the plasma of mice with cardiac insufficiency are reduced." (PMID 34799616, 2021). "In addition, interleukin 6 (IL-6), another classic cytokine mainly derived from monocytes, could be significantly increased in patients with left ventricular systolic dysfunction without clinical symptoms, and may be a sensitive indicator for the early diagnosis of heart failure." (PMID 34869661, 2021). "This could trigger the production of pro-inflammatory mediators, such as IL1, IL6, TNF-α, and TGF-β, contributing to cardiac remodeling and heart failure." (PMID 34884782, 2021). "The probability of no hospital admission for heart failure in the first year was lower in the group with elevated IL-6 (log-rank test = 0.055); in other words, the free time of hospitalization was lower in this group." (PMID 33535417, 2021). "Interleukin-6, TNF-α and adiponectin correlated with heart failure severity parameters." (PMID 34685378, 2021). "Furthermore, levels of IL-6, TNF-α and adiponectin increased according to NYHA class and correlated with all heart failure severity parameters (LVEF, mPAP, PCWP, and BNP), except TNF-α, which did not correlate with PCWP." (PMID 34685378, 2021). "There was the decrease in cardiac failure parameters such as: creatine kinase, MB isoenzyme of creatine kinase and lactate dehydrogenase, as well as the extenuation of cardiac mRNA expression for tumor necrosis factor α (TNF-α) and interleukin 6 (IL-6)." (PMID 34576213, 2021). "Although at this moment, it is not clear if IL-6 is the only valuable biomarker of heart failure or it is only pathophysiologically involved in heart failure." (PMID 33036382, 2020). "Despite numerous experimental and clinical studies, the role of IL-6 on the development of heart failure has not yet been fully elucidated." (PMID 33036382, 2020). "Finally, our data are consistent with the role of inflammation with the initiation of heart failure in PP2C-TG and DT: parameters such as IL-6 are higher in PP2C-TG than in WT." (PMID 33597873, 2020). "Whereas the inhibition of the renin–angiotensin–aldosterone pathway is an established therapy in heart failure, the role of IL-6 has not been fully elucidated." (PMID 33122738, 2020). "SI was shown to increase the expression levels of Nrf2 and SOD and to reduce the expression of C-reactive protein, 8-isopropanol, MDA, IL-6, and TNF-α in patients with heart failure, improving the antioxidant capacity of patients with IC by upregulating Nrf2 and treating heart failure." (PMID 33062142, 2020). "The aim of this study is to assess the circulating level of interleukin (IL)-6 and IL-18 in patients with ischemic and idiopathic DCM who suffer from heart failure symptoms in order to determine the effects of two main etiologies of DCM on expression of these two interleukins." (PMID 31384408, 2019). "Nevertheless, IL-10 is considered as a cardio-protective cytokine and increased levels of IL-10 in heart failure may be seen as a compensatory mechanism to counter deleterious effects of cytokines, such as TNF-α or IL-6." (PMID 30177883, 2018).
heart failure (continued). "Also included in this group, tumor necrosis factor (TNF)-α and interleukin (IL)-6, key inflammatory cytokines involving in the progression of CVD and heart failure, can be upregulated by a number of uremic toxins." (PMID 30200452, 2018). "Without heart failure however, IL-6 seems to exert protective role on the skeletal muscles, stimulates hypertrophy and myogenesis, and regulates the energy metabolism." (PMID 29093735, 2017). "The covariates were age, sex, GFG, LVEF, NYHA class (which are known to have an impact on survival of patients with heart failure), and parameters which appeared to be significant in univariate regression analysis (APN, IL-6, CD 3+ cell count, and average global strain)." (PMID 29318144, 2017). "High levels of IL-6 and TNF-α predicted incident heart failure." (PMID 25722960, 2015). "Although not within the PVN, a handful of previous reports showed that systemic injection of anti-TLR4 antibody decreases serum levels of IL-6 in SHR and systemically infused TLR4 antagonist reduces serum levels of inflammatory markers in heart failure animals." (PMID 25879545, 2015). "In the present study, TPT treatment may decrease plasma TNF-α, and IL-6 levels, indicating that TPT delay heart failure by inhibiting TNF-α, and IL-6 secretion, and improving immunity system, and strengthen myocardial contractility." (PMID 22569420, 2012). "Furthermore, IL-6 and TNF-α have been shown to be independent predictors of mortality in heart failure." (PMID 19909503, 2009). "Analyzed biochemical variables will include heart failure biomarkers, such as NT-proB-type natriuretic peptide (NTproBNP), troponin (hs-TnI), and inflammation markers, such as polymerase chain reaction (PCR), tumor necrosis factor-alpha (TNF-alpha), and interleukin 6 (IL-6)." (PMID 36923954, 2023). "However, since IL-6 has a negative inotropic effect, its function is still unclear, suggesting the possibility of detrimental impacts by IL-6 driving hypertrophy toward heart failure." (PMID 37443814, 2023). "However, our study did not evaluate the presence of heart failure at 2-year follow-up, and IL-6 levels exhibited a significant negative correlation with the global LV function, expressed by EF, as early as one month following the MI." (PMID 35268316, 2022). "Moreover, targeting inflammatory cytokines and chemokines, such as IL-1, IL-6, CCL2, TGF-β, TNF-α, could be helpful in heart failure treatment." (PMID 34387811, 2022). "In the group of inflammatory biomarkers of heart failure are some traditional biomarkers, such as C-reactive protein (CRP) and high-sensitivity C-reactive protein (hs-CRP), tumor necrosis factor-alpha (TNF-α), interleukin-6 (IL-6), as well as some new biomarkers." (PMID 35626917, 2022). "An uncontrolled production of proinflammatory mediators, such as IL-6, IL-1β, IFN-γ, and TNF-α, drives hyperinflammation during severe COVID-19 infection, leading to cardiovascular and respiratory complications, including ARDS, disseminated intravascular coagulation, and heart failure." (PMID 35955801, 2022). "However, we did not observe a significant difference in the serum levels of IL-6 between heart failure patients and control individuals statistically, although they were markedly increased in male and female patients." (PMID 33479413, 2021). "Thus, IL-6 could be useful in identifying asymptomatic patients with MetS and LVDD and applying lifestyle measures to prevent overt heart failure development." (PMID 31275453, 2019). "Visfatin increase in type-2 DM patients was related to heart failure and acute coronary syndromes; visfatin appears to mediate vascular endothelial inflammation by inducing the expression of adhesion molecules (VCAM-1 and ICAM-1) and pro-inflammatory cytokines such as IL-1β, IL-6, and TNF-α." (PMID 28590452, 2017). "However, the expressions of IL-1β and IL-6 were not different between in MI-induced heart failure treated with TLR4-SiRNA and that treated with hGAPDH-SiRNA for 2 weeks." (PMID 23874864, 2013).
heart failure (continued). "However, there are also indications that IL-6 might function as a biomarker of cardiac injury rather than playing a critical role in cardiac protection or the development of heart failure." (PMID 35163735, 2022). "Compared with a rat model of cardiac failure and miR-30b-5p-non-loaede NP groups, the expression of cardiac hypertrophy markers (ANP, BNPβ-MHC) and inflammatory factors (IL-1β, IL-6) were significantly decreased." (PMID 34658880, 2021). "We found negative correlation between myocardial PPARγ expression and IL-6 level only before CABG, when none of patients had features of heart failure." (PMID 29093735, 2017). "Various studies have identifiedconnections between IL-6 levels and CAD severity and have shown that patients with pre-existing CAD had increased levels of IL-6 compared to patients without CAD, coronary events mortality and progression to heart failure." (PMID 37323554, 2022). "Therefore, overall, our present and the reported findings suggest that inhibition of IL-6, α-SMA and collagen expression by hyperthermia might be widely applicable for non-pharmacological treatment of cardiac fibrosis and heart failure." (PMID 29674727, 2018). "Moreover, since the role of TNF-α and IL-6 SNPs in the pathogenesis of CHD has remained inconclusive, investigating patients with IHD and no heart failure might have given more conclusive results." (PMID 29849987, 2018).